IL6 (interleukin 6)
Diseases named in the same sentence as IL6 in open-access papers (continued):
Sharing a sentence is not in itself a finding about the gene and the disease.
depression (continued). "However, other studies have reported that the concentrations of IL-1β, IL-6 and/or CRP in the serum or cerebrospinal fluid were positively correlated with depression severity only, or more profoundly in females." (PMID 33672958, 2021). "Animal research also showed that treatment with agomelatine reversed the signs of anxiety and depression, and decreased the cytokines (tumor necrosis factor-α [TNF-α], interleukin 6 [IL-6], and IL-1β), thiobarbituric acid reactive substances, as well as caspase-3 activity." (PMID 34079622, 2021). "The results of our PPI network analysis that IL-6 and TNF are the top five targets also confirmed this view, indicating that they may play an important role in the treatment of DM and depression." (PMID 34875999, 2021). "Several cytokines and chemokines have been identified as biomarkers or therapeutic targets of NPSLE; in particular, the levels of type 1 interferons, TNFs, and IL-6 are elevated in SLE patient’s cerebrospinal fluid (CSF), and these factors contribute to the pathology of depression." (PMID 34804003, 2021). "Therefore, the relation between BDNF, IL-6, TNF-α, and depression severity before, during, and following ECT in severe LLD will be examined." (PMID 34841285, 2021). "Therefore, IL-6/IL-6R alterations in schizophrenia may be more closely aligned to vulnerability to infection as well as atopic/contact dermatitis, while IL-6/IL-6R alterations in depression may be more closely aligned to that found in rheumatoid arthritis and cardiovascular disease." (PMID 34280516, 2021). "Moreover, has_circ_0014220, has_circ_0014221, and their host gene S100A9 enriched in the IL-17 signaling pathway, augmented levels of the inflammatory cytokines IL-6, TNF-α, and IFN-γ in depression patients as well as tumor-bearing mice with CUMS." (PMID 34650925, 2021). "Depression can lead to the upregulation of tumor necrosis factor (TNF) and interleukin (IL)-6." (PMID 34439637, 2021). "Thus, proinflammatory cytokines and molecules such as TNF-α, IL-6, interleukin 1 (IL-1), soluble interleukin 2-receptor (sIL-2R), and C-reactive protein (CRP) measured in serum are increased in patients with depression as compared to healthy subjects." (PMID 34764926, 2021). "is that increased IL-6 levels in response to ECT induce neuroplastic change and the eventual decrease in IL-6 and TNF-α levels could be related to recovery of depression or to an anti-inflammatory response of ECT." (PMID 34841285, 2021). "IL-6 and TNF-α may play a more important role than other cytokines in the pathogenesis of depression." (PMID 34733143, 2021). "Higher IL-6 and CRP can predict the development of depression." (PMID 34054732, 2021). "Moreover, correlations between IL-6 activity, acute phase proteins, and hyperactivity of the hypothalamic-pituitary-adrenal (HPA) axis were suggested in severe depression." (PMID 33593388, 2021). "Excessive secretion of IL-1β, IL-6, and TNF-α triggers depression-like symptoms." (PMID 33584387, 2021). "In the Netherlands Study of Depression and Anxiety (NESDA), a cohort consisting almost 3000 participants, no indications were found in KYN/Trp ratio for mediating the relationship between changes in IL-6 levels and depressive symptoms." (PMID 34072767, 2021). "Chinese studies did not confirm the increased concentration of IL-6 in the blood of people with depression." (PMID 34945157, 2021). "Surprisingly, in a study on the use of ketamine in the treatment of patients with treatment-resistant depression, the opposite result was obtained—an increase in IL-6 concentration, which did not correlate with the improvement of the condition of patients." (PMID 34945157, 2021). "In accordance with the findings, the IL-1β, TNF-α, and IL-6 levels in the group with depression exceeded those without depression, and the high level of IL-6 contributed to memory impairment in the depressive group." (PMID 34299040, 2021).
depression (continued). "Most of the inflammatory markers involved in Psoriasis (TNF-α, IL-2, IL-6, IL-23, IL-1β, IL-10), and increased serotonin transporters (5-HTT) were also found in the pathogenesis of depression, showing the immune-inflammatory linkage between psoriasis and major depression." (PMID 34183985, 2021). "IL-6 levels are also significantly higher in pwMS with depression compared to those without depression." (PMID 34589733, 2021). "A key role of the proinflammatory cytokines IL-6 and TNF-α has in fact been described in depression, moreover, both in patients and experimental models a clear relationship between low levels of BDNF and the presence of anxiety and depression has been suggested." (PMID 34638592, 2021). "Notably, increased peripheral levels of IL-1β, and of IL-1β and IL-6, but unchanged TNF-α, were reported in patients with AD or major depression, respectively." (PMID 34109176, 2021). "In another study, they compared physically active chronic cannabis users (at least once per week for the past 6 months) and non-users in terms of the presence of depression and immune health indicated partly by IL-6." (PMID 34072767, 2021). "A recent RCT of anti-IL-6 monoclonal antibody sirukumab showed improvement in anhedonia but did not report significant difference in overall depression severity." (PMID 34135474, 2021). "The final model for hot/coldness in hands/feet included worse fatigue/anxiety/depression (26%), higher pro-inflammatory IFN-γ (18%), worse baseline neuropathy (14%), taxane chemotherapy (11%), lower IL-6 (9%), lower anti-inflammatory IL-10 (9%), and lower BMI (6.5%)." (PMID 34191201, 2021). "Inflammatory cytokines like IL-6 and TNF-α are involved in the pathogenesis of depression and have been found to increase in previous animal models of depression and in patients with clinical depression." (PMID 33987106, 2021). "Among women who have recently given birth, those with a lifetime history of major depression have greater increases in both serum IL-6 and soluble IL-6 receptors after delivery than women without a history of depression." (PMID 34777037, 2021). "Therefore, there have been calls for peripheral blood IL-1β, IL-6, and TNF as biomarkers of depression patients." (PMID 34650925, 2021). "Thus, IL-6, IL-17, and TNF levels are higher in patients with depression compared with healthy controls." (PMID 34124110, 2021). "Similarly, in salivary samples significant decrease in IL-6 and TNF-α were reported in depressed participants but the levels of cortisol were similar in patients remitted from major depressive disorder when compared to controls." (PMID 35002817, 2021). "Depression has sustained a series of inflammatory state, and promoted the increase of inflammatory markers, such as tumor necrosis factor-α (TNF-α), C-reactive protein (CRP) and interleukin 6 (IL-6)." (PMID 34421539, 2021). "In this way, IL-6 inflammatory pathways may affect shared behavioral outcomes by ethanol and HFD consumption (anxiety, depression, craving)." (PMID 34067897, 2021). "Additionally, given interest in other potential markers of inflammation in relation to depression treatment response, we also explored relationships between several other inflammatory markers including CRP, IL-6, IL-10, TNF-α, and ketamine treatment outcome." (PMID 33723220, 2021). "Additionally, plasma inflammatory factor levels of IL-6, IFN-γ, and TNF-α were significantly increased in the depression group compared with the healthy ones." (PMID 34650925, 2021). "In comparison with healthy controls, patients with major depression have higher concentrations of inflammatory cytokines, including tumor necrosis factor (TNF)-α, interleukin (IL)-1β, IL-6, and C-reactive protein (CRP), while lower IL-10 concentration in blood." (PMID 34975477, 2021). "Based on these reports, it was suggested that peripheral blood IL-1β, IL-6, TNF, and CRP could constitute reliable biomarkers of inflammation in patients with depression." (PMID 32380663, 2020).
depression (continued). "Patients with HD had significantly more depression (p < 0.05), higher scores on the CTQ assessment (p < 0.001), higher levels of plasma ACTH after the DST (p < 0.01) and TNF-alpha (p < 0.0001), but lower levels of plasma IL-6 (p < 0.001)." (PMID 31542994, 2020). "Much of the interest in inflammation and depression has been focused on cytokines, which mediate the innate immune response, including tumor necrosis factor alpha (TNF-α), and IL-6, which appears to be one of the most reliable peripheral biomarkers in major depression." (PMID 33324599, 2020). "Most studies investigating inflammatory markers of depression have focused on CRP and IL-6." (PMID 33255237, 2020). "Importantly, the improvement in depression correlated with normalization of inflammatory biomarkers (e.g., IL-6) and insulin resistance, suggesting an intriguing link among PPAR-γ-activation, depression, inflammation, and metabolism." (PMID 32120979, 2020). "Another study obtained serum sample at the time of delivery and found IL-6 levels at delivery were not related to depression during the first six months after delivery." (PMID 32235786, 2020). "Numerous studies conducted on patients meeting the criteria of the Diagnostic and Statistical Manual of Mental Disorders (DSM) for major depression have found significant increases in plasma or serum levels of CCL2, IFNγ, IL-1α, IL-1β, IL-2, IL-6, IL-8, IL-12 and TNF-α, together with CRP." (PMID 32545890, 2020). "A different study found that pancreatic cancer patients with depression had significantly increased levels of IL-6 than both healthy subjects and cancer patients without depression, further adding to this theory." (PMID 32850269, 2020). "The fatigue dimensions, but not the severity of the depression, showed differences in IL-6 concentrations." (PMID 32528052, 2020). "In major depression, significant associations were established between increased plasma KOR/MOR levels, on the one hand, and elevated plasma IL-6 and IL-10, on the other, indicating that immune - EOS interactions play a role in the pathophysiology of depression." (PMID 32858974, 2020). "Clinically anxious individuals have also been found to have higher levels of IL-6 and lower levels of morning cortisol, even in the absence of depression." (PMID 33297471, 2020). "Astrocyte activation could result in the release of inflammatory cytokines, including IL-1β, IL-6, and TNF-α, which could promote the symptoms of depression." (PMID 32321532, 2020). "Three meta-analyses have verified that people with MDD show elevated serum/plasma IL-6 levels compared to people without depression." (PMID 32235786, 2020). "In the same sample, we also find that blood levels of CRP, IL-3, IL-6, IL-12, IL-18, sIL-2R and TNF α are significantly elevated in patients with depression with medium-large effect sizes (range 0.54–1.97), and that these findings are robust to a range of potential confounds and moderators." (PMID 32113908, 2020). "Activated microglia synthesizes IL-6 and TNF-α, as antineurogenic signals, which can interact directly with neural progenitor cells and determine a decrease in neurogenesis also on the brain structures that regulate emotions in depression." (PMID 32545890, 2020). "Therefore, the dysfunction of glucose homeostasis signaling mediated by IL-6 eventually affects the transcription of GLUT4, partly elucidating the common biological mechanism of depression and diabetes." (PMID 32655424, 2020). "Most studies found that patients comorbid with depression have elevated IL-6 levels than those without depression." (PMID 32235786, 2020). "Enhanced inflammation reported in the melancholic subtype in certain studies (e.g., elevated CRP, IL-6, TNF-α) could reflect the characteristics of the study cohort (e.g., patients with more severe symptoms of depression, inpatient)." (PMID 33255237, 2020).
depression (continued). "However, there is increasing evidence of a bi-directional relationship between inflammatory markers, such as IL-6 and TNF-α, with depression." (PMID 31899521, 2020). "Furthermore, some reports pointed the elevation of inflammatory cytokines [mainly interleukin-1 (IL-1), interleukin-6 (IL-6), and tumor necrosis factor-α (TNF-α)] in depression." (PMID 33329109, 2020). "Our findings of increased inflammation (IL-6, CRP, MCP4, TARC) also align with previous research finding increased pro-inflammatory cytokines in treatment-resistant versus responsive patients with depression." (PMID 33276697, 2020). "In particular, tumor necrosis factor alpha (TNFα), interleukin-2 (IL-2), interleukin-6 (IL-6), interleukin-13 (IL-13), interleukin-18 (IL-18), C-reactive protein (CRP), chemokine-2 (CCL2), and chemokine-11 (CCL11) are elevated in depression based on multiple meta-analyses." (PMID 32351416, 2020). "At the same time no direct correlation was found between plasma and CSF concentrations of IL-6 in subjects with suicide attempts, nor such correlation was detected for scores of depression severity." (PMID 32732883, 2020). "Furthermore, the levels of IL-1β, IL-6, TNF-α, and TGF-β are positively correlated with the symptoms of depression." (PMID 33613190, 2020). "Moreover, IL-6 together with TNF-α is considered a mediator of systemic COPD effects (cachexia, skeletal muscle dysfunction, cardiovascular diseases, depression, hypodynamia, and osteoporosis), leading to an unfavorable outcome." (PMID 32089881, 2020). "Furthermore, the concentrations of interleukin-6, C-reactive protein, and tumor necrosis factor-α are increased in patients with CHD with co-morbid depression." (PMID 33584362, 2020). "There is now evidence that major depressive disorder (MDD) is characterized by activation of the immune-inflammatory response system, as indicated by increased levels of pro-inflammatory cytokines including interleukin (IL)-6 and IL-10." (PMID 32093807, 2020). "Moreover, increased expression of various innate immune genes, including IL-1β, IL-6, TNF, TLR3, and TLR4, have been found in post-mortem brain samples from suicide victims that had depression." (PMID 32380663, 2020). "The result showed that patients with depression had significantly higher levels of serum IL-6 and IL-6-to-IL-10 ratios compared to patients without depression." (PMID 32235786, 2020). "IL-1β, IL-6, and TNF-α are the most generally demonstrated proinflammatory cytokines in depression." (PMID 32596383, 2020). "In addition, IL-6 is involved in neurogenesis, neural mediation, and TNF-α plays a major role in the brain’s immune response and is an important indicators for depression." (PMID 32922291, 2020). "IL-6, TNF-α, and corticosterone are highly expressed in patients with anxiety and depression." (PMID 32158447, 2020). "Patients with cardiovascular disease and the diagnosis of PTSD had an enhanced IL6 response to stressful tasks (“mental stress”) compared patients without PTSD, with similar findings in individuals with early life stress, and vulnerability to depression." (PMID 32916852, 2020). "In this study, we found that the ingestion of L. intestinalis and L. reuteri did not induce depression- and anhedonia-like behaviors, increase plasma IL-6 levels, or reduce synaptic protein expression in the PFC in vagotomized mice." (PMID 32799901, 2020). "Therefore, with regards to shared inflammatory mechanisms underpinning the comorbidity between depression and CHD it is likely that IL-6 is a key driver." (PMID 30886334, 2020). "Furthermore, our findings of increased mean levels of CRP, IL-6, IL-12 and TNF α in depression replicate previous meta-analytical findings; the same can be said of no changes in levels of TGF β." (PMID 32113908, 2020). "In addition, PI3k-Akt pathway controlled BDNF (such as IL-6, TNF-α) to reverse depression-like behavior in a neurotrophic and neuroprotective way." (PMID 32997725, 2020).
depression (continued). "Moreover, serum IL-6 and CRP levels were observed to be positively correlated (r = 0.452; p = 0.043) with each other in depression." (PMID 30899619, 2019). "In contrast, splenic T-lymphocyte expression of IL-6 or IL-17A did not correlate with anxiety-like behavior indices but IL-6 positively correlated with depression-like behavior indices, which has been previously reported." (PMID 31139062, 2019). "Corticosterone, IL-6, and TNF-α were highly expressed in patients with anxiety/depression." (PMID 30979031, 2019). "In order to gain further insight into the relationship between inflammation and depression, we present another longitudinal study based on the ALSPAC cohort that examines the relationships between IL-6 and CRP at age 9 years and 19 specific symptoms of depression assessed at age 18 years." (PMID 30414442, 2019). "Also, TNF-α release as an inflammatory marker has been documented in patients with idiopathic major depression additional to circulating interleukin (IL)-1, IL-6, and C-reactive protein (CRP), which correlates with depression severity." (PMID 30866491, 2019). "Interestingly, ROS seems to activate ABL1/NF-κB1-related cytokines (IL-6, IL-1β, and COX2), thus involving itself in the process of depression." (PMID 31396300, 2019). "It was found that negative emotions, such as bad mood, depression and anxiety augment the production of IL-6 (found in NK cells) and produce inflammatory level, thereby producing heightened responsiveness to subsequent stressful events." (PMID 31150403, 2019). "It was found that SNS may up-regulate CYP1A2, CYP2D1, CYP2E1, and CYP3A2 activity to reduce IL-6 and TNF-α expression, as well as up-regulation of BDNF and its receptor TrkB, reduce IL-1β, IL-6, and TNF-α expression to treat depression." (PMID 32009949, 2019). "Nevertheless, concerning depression, there can be no doubt that IL-6 trans-signaling has important pathophysiological consequences (see Section 3.1 and Section 3.2)." (PMID 31362361, 2019). "A significant elevation of serum IL-6 levels was observed in patients with major depression, but the change in serum CRP levels was not significantly different between the groups." (PMID 30899619, 2019). "It is also of note that we have recently published, in a different but overlapping sample of patients taking IFN-α, that the IFN-α-induced increase in IL-6 levels is not related to the development of IFN-α-induced depression." (PMID 30567628, 2019). "According to the current literature, it seems that peripheral levels of interleukin (IL)-6, IL-10, IL-12, IL-13, and tumor necrosis factor (TNF)-α are elevated and that interferon (IFN)-γ levels are lower in patients with depression compared to healthy controls." (PMID 30792669, 2019). "One of them is the NF-κB pathway, from where MAPK, JAK/STAT, JNK, or ERK may be activated; and depression-related cytokines such as tumor necrosis factor (TNF)-α, IL-1β, and IL-6 production may increase." (PMID 31491962, 2019). "Carriers of G allele in IL6-174 have less depressive symptoms after interpersonal stress, but the IL6 genotype does not alleviate the impacts of non-interpersonal stress exposure (i.e., financial, work and health-related difficulties) on depression." (PMID 31970102, 2019). "In addition, the expression of IL-1β, IL-6, and TNF-α was also increased in postmortem brain samples from suicide victims that suffered from depression." (PMID 31068207, 2019). "Similarly, production of IL-6, IL-10, and TNF-α levels have been shown to be increased in animal models for depression using acute or restraint stress, whereas IFN-γ production was significantly decreased by restraint stress in rats." (PMID 30792669, 2019). "Moreover, observing elevated peripheral IL-6 and CRP levels would have promoted the psychoneuroimmunology theory as a contributing factor for the development of depression." (PMID 30899619, 2019).